TRPA1 (transient receptor potential cation channel subfamily A member 1)
Diseases named in the same sentence as TRPA1 in open-access papers (continued):
Sharing a sentence is not in itself a finding about the gene and the disease.
scleroderma (2 papers, 2023 to 2024). Scleroderma is a rare autoimmune connective tissue disorder characterized by abnormal hardening of the skin and, sometimes, other organs. "In a study on scleroderma dermal fibrosis, markers of M2-type macrophage activation, which are crucial for tissue fibrosis, were reduced in TRPA1-deficient mice treated with bleomycin." (PMID 38635081, 2024). "Wild type and TRPA1-deficient mice were challenged with intradermal bleomycin injections to induce a scleroderma-mimicking disease." (PMID 36698198, 2023). "In the present study, we investigated the role of TRPA1 in bleomycin-induced skin fibrosis mimicking scleroderma." (PMID 36698198, 2023). "In the present study, we show first evidence of the involvement of TRPA1 in bleomycin-induced model of scleroderma." (PMID 36698198, 2023). "In conclusion, the results indicate that interfering TRPA1 attenuates fibrotic and inflammatory responses in bleomycin-induced scleroderma." (PMID 36698198, 2023). "Therefore, TRPA1-blocking treatment could potentially alleviate M2 macrophage driven diseases like systemic sclerosis and scleroderma." (PMID 36698198, 2023). "We propose that TRPA1 influences inflammatory responses in bleomycin-induced scleroderma by boosting activation of M2-type macrophages and other cell types including fibroblasts leading to fibrosis; therefore, TRPA1 antagonists may have therapeutic potential in fibrosing diseases." (PMID 36698198, 2023). "Therefore, we set out to compare mice with functional and non-functional TRPA1-gene in bleomycin-induced model of scleroderma and complemented the study with in vitro experiments in cultured mouse macrophages." (PMID 36698198, 2023).
systemic inflammatory response syndrome (2 papers, 2017 to 2021). SIRS is a serious condition related to systemic inflammation, organ dysfunction, and organ failure. "The TRPA1 agonist cinnamaldehyde can modulate the LPS-induced systemic inflammatory response syndrome through TRPA1-dependent and TRPA1-independent mechanisms." (PMID 33810314, 2021). "In an animal model, cinnamaldehyde, a pungent compound which is also a TRPA1 agonist, reduced the severity of LPS-induced systemic inflammatory response syndrome through TRPA1-dependent but also TRPA1-independent mechanisms." (PMID 28642799, 2017).
abscess (1 paper, 2024). An inflammatory process characterized by the accumulation of pus within a newly formed tissue cavity which is the result of a bacterial, fungal, or parasitic infection or the presence of a foreign body. "While deletion of TRPV1 did not affect lesion size or inflammatory markers, TRPA1−/− mice demonstrated significantly reduced infection severity and abscess size." (PMID 39337422, 2024). "Treatment with natural inhibitors of TRPA1 with or without blockade of TRPV1 also reduced abscess size." (PMID 39337422, 2024). "Our data suggest that TRPA1 influences both DAG and PI3K, resulting in the expected reduction of HIF1α activation, alteration in glycosaminoglycan metabolism, and ultimately worsened MRSA control due to altered abscess formation." (PMID 39337422, 2024).
acute tubular necrosis (1 paper, 2021). "Patients with high expression of TRPA1 in the renal tubule were highly likely to show nonrecovery of the renal function, which hinted that renal tubular TRPA1 was a risk factor for the recovery of renal function from acute tubular necrosis (ATN)." (PMID 33810314, 2021).
alcoholic liver diseases (1 paper, 2026). A disorder caused by damage to the liver parenchyma due to alcohol consumption. "Transient receptor potential ankyrin 1 (TRPA1) is a non-selective cation channel, and its activator, the alcohol breakdown product acetaldehyde, plays a key role in the pathomechanism of alcoholic liver disease (ALD)." (PMID 41827854, 2026).
alcoholic neuropathy (1 paper, 2023). "In the alcoholic neuropathy and partial sciatic nerve ligation model, the TRPA1 total deletion or its specific silencing in Schwann cells prevented the development of mechanical and cold allodynia." (PMID 37296632, 2023).
anaphylaxis (1 paper, 2021). An acute hypersensitivity reaction that occurs from exposure to an allergen. "The protective role of TRPA1 in anaphylaxis was later questioned in a different animal anaphylaxis model, oxygen-induced anaphylaxis (OIA)." (PMID 34768891, 2021).
angina (1 paper, 2022). "H2O2 is an endogenous agonist of TRPA1, and our study successfully demonstrated its role in angina following exercise." (PMID 35269964, 2022). "To further determine the essential role of TRPA1 in angina, we used TRPA1−/− mice for the additional experiment." (PMID 35269964, 2022). "Overall, these results strongly suggest that TRPA1 channels, which are expressed on cardiac sensory neurons, are involved in exercise-induced angina development." (PMID 35269964, 2022). "Taken together, the TRPA1 channel mediates angina following exercise, suggesting a possible molecular mechanism of angina after revascularisation therapy." (PMID 35269964, 2022). "As an important function, TRPA1 mediates hypoxia-induced dysaesthesia in the somatosensory system; however, this putative mechanism in the onset of angina remains obscure." (PMID 35269964, 2022). "Moreover, FTE evoked hydrogen peroxide (H2O2) production in the I/R-injured heart, inducing angina through TRPA1 activation on cardiac sensory fibres." (PMID 35269964, 2022). "Overall, TRPA1 may play a critical role in the generation of exercise-induced angina after a myocardial I/R injury." (PMID 35269964, 2022). "Our study revealed that TRPA1−/− mice displayed a completed anti-angina effect following exercise." (PMID 35269964, 2022). "Notably, the treatment of a ROS scavenger or TRPA1-/- mice successfully alleviates exercise-induced angina after an I/R injury." (PMID 35269964, 2022). "Moreover, exercise induces H2O2 production in the I/R-injured heart, thereby evoking angina through TRPA1 activation on cardiac sensory fibres." (PMID 35269964, 2022). "To determine whether TRPA1 contributes to angina after FTE, we systemically applied A-967079, a selective TRPA1 antagonist, to the animals 30 min before FTE." (PMID 35269964, 2022). "Therefore, cardiac sensory fibres may respond to endogenous H2O2 through TRPA1 activation, leading to angina." (PMID 35269964, 2022). "Considering that the TRPA1-selective antagonist is not a clinically applicable medication, free radical scavengers might have the potential to treat patients with angina after revascularisation therapy." (PMID 35269964, 2022).
Anorexia (1 paper, 2022). Lack of desire to eat (loss of appetite). "Subsequently, we demonstrated that DON elicited brain-gut peptide-driven anorexia and emesis in a murine anorexia model and mink emesis model by activating the Calcium-sensing receptor (CaSR) and a transient receptor potential (TRP) channel named TRP ankyrin 1 (TRPA1), respectively." (PMID 35737032, 2022).
Ataxia (1 paper, 2017). Ataxia refers to impaired coordination of voluntary muscle movement. "In the classic hens OPIDN model, malathion causes nerve injuries and ataxia to a similar level as the positive inducer tri-ortho-cresyl phosphate (TOCP), which also activates TRPA1 channel." (PMID 28894590, 2017).
bacterial sepsis (1 paper, 2023). "Afferent vagus nerve TRPA1 signaling also inhibits endotoxin-stimulated cytokine storm and significantly reduces the lethality of bacterial sepsis." (PMID 36650454, 2023). "Vagus nerve TRPA1 signaling also inhibits endotoxin-stimulated cytokine storm and significantly reduces the lethality of bacterial sepsis." (PMID 36650454, 2023).
behavioural disorders (1 paper, 2021). "Thus, TRPA1 might be a promising drug target for the treatment of certain behavioural disorders." (PMID 34959735, 2021).
brain trauma (1 paper, 2017). "It is possible that TRPA1 is activated during pathological conditions such as oedema and brain trauma." (PMID 28424320, 2017).
brain tumors (1 paper, 2023). "In accord, selective TRPA1 stimulation to promote caspase activation and cell death could exacerbate oxidative stress (e.g., in brain tumors), possibly further boosting cancer cell elimination." (PMID 37174661, 2023).
chronic asthma (1 paper, 2021). An asthma that is characterized by the development of persistent airway inflammation and recurrent attacks of breathlessness and wheezing, which vary in severity and frequency. "However, treatment directed at TRPV1 significantly alleviated IL-4, IL-5, and IL-13 level in a chronic asthma murine model, while conversely TRPA1 promoted OVA-induced IL-4 production during acute allergic lung inflammation." (PMID 34099759, 2021).
Chronic colitis (1 paper, 2022). A chronic inflammatory disease of the large intestine (colon, cecum and rectum). "TRPA1 has previously been suggested to be protective against fibrosis in intestinal myofibroblasts, both in vitro and in a mouse model of chronic colitis." (PMID 36038551, 2022).
Chronic constipation (1 paper, 2023). Constipation for longer than three months with fewer than 3 bowel movements per week, straining, lumpy or hard stools, and a sensation of anorectal obstruction or incomplete defecation. "Therefore, TRPA1 agonists may be clinically useful in postoperative ileus and atonic colon/chronic constipation, also known as “lazy bowel syndrome”." (PMID 37240443, 2023).
cocaine addiction (1 paper, 2024). "In this study, we explored the role of TRPA1 channels in modulating excitatory synaptic transmissions and cocaine addiction-related behavior as well as dopamine release." (PMID 38822069, 2024). "Together, these data suggest a mechanism whereby TRPA1-dependent regulation of dopaminergic activity in the NAc impacts cocaine addiction-related behavior." (PMID 38822069, 2024).
cognitive decline (1 paper, 2024). "Further research is necessary to explore the mechanism of TRPA1 on the relationship between olfactory and cognitive decline." (PMID 38915349, 2024).
congestive heart failure (1 paper, 2024). Failure of the heart to pump a sufficient amount of blood to meet the needs of the body tissues, resulting in tissue congestion and edema. "This suggests that pharmacological targeting of TRPA1 may represent a novel approach for managing pressure overload-induced cardiac diseases, such as hypertrophic cardiomyopathy and congestive heart failure." (PMID 39323758, 2024).
degenerative disc disease (1 paper, 2019). "TRPA1 might be expressed in developing IVD, downregulated during its maturation, and upregulated again in degenerative disc disease, participating in matrix homeostasis." (PMID 30974795, 2019). "However, follow-up studies with larger sample sizes are needed to fully elucidate the role of TRPA1 and other TRP channels in degenerative disc disease." (PMID 30974795, 2019).
demyelination (1 paper, 2023). "The main goal of this research was to assess the neuroprotective effects of IVM and nano-IVM in CPZ-induced demyelination mice and to observe the role of the TRPA1/NF-kB/GFAP signaling pathway." (PMID 37886003, 2023).
Duchenne muscular dystrophy (1 paper, 2019). Duchenne muscular dystrophy (DMD) is a neuromuscular disease characterized by rapidly progressive muscle weakness and wasting due to degeneration of skeletal, smooth and cardiac muscle. "Finally, it has been more recently hypothesised that TRPA1 may be beneficial in delaying the progression of Duchenne’s muscular dystrophy as tetrahydrocannabidivarin showed improving myotube formation through the activation of TRPA1." (PMID 31197115, 2019).
enteritis (1 paper, 2023). Inflammation of the small intestine. "According to the literature TRPA1 plays dual effects (pro-inflammatory and anti-inflammatory) in the occurrence and development of enteritis." (PMID 36875034, 2023). "Therefore, TRPA1 plays a bidirectional regulatory role in enteritis, which is dependent on the disease stage." (PMID 36875034, 2023). "The mediating effect of TRPA1 on the pathogenesis of enteritis remains unclear." (PMID 36875034, 2023).
eosinophilia (1 paper, 2025). "However, cold air exposure failed to augment airway eosinophilia in response to papain in Trpa1 KO mice." (PMID 41322401, 2025).
ependymoma (1 paper, 2021). A WHO grade II, slow growing tumor of children and young adults, usually located intraventricularly. "TRPV2, TRPV4, and TRPA1 were expressed to similar levels across the two ependymoma subgroups." (PMID 33477420, 2021).
gastritis (1 paper, 2020). Inflammation of the stomach. "These are the first data for the concentration- and duration-dependent changes in the IAA-induced gastritis in rats accompanied by TRPA1 upregulation, therefore, its therapeutic potential in gastritis should further be investigated." (PMID 32764237, 2020). "There are no data on the expression and function of the TRPA1 channel in gastritis and only little information is available on TRPV1." (PMID 32764237, 2020). "Therefore, our aim was to characterize a translationally relevant gastritis model using the irreversible sulfhydryl-group blocker IAA and to investigate the expression changes of TRPA1 and TRPV1 in this model." (PMID 32764237, 2020). "Therefore, we characterized a translational gastritis model using iodoacetamide (IAA) and investigated TRPA1/V1 expressions." (PMID 32764237, 2020). "The role of TRPA1 and TRPV1 in gastritis might also be attributed to the mediation of inflammatory visceral hyperalgesia and abdominal pain." (PMID 32764237, 2020).
helminth infection (1 paper, 2024). "Newer data suggest the possible beneficial role of TRPA1 in the control of parasitic infections; thus, further studies should compare if the processes that are deleterious for MRSA control may be of evolutionary benefit in helminth infection." (PMID 39337422, 2024).
hyperlipidemia (1 paper, 2020). "Administration of the TRPA1 channel antagonist HC030031 or knockout of the TRPA1 [TRPA1 (-/-)] gene in apoE (-/-) mice can exacerbate atherosclerotic lesions, hyperlipidemia, and systemic inflammation." (PMID 32903613, 2020).
ischemic disease (1 paper, 2024). Lack of blood supply to an area of the body, resulting in impairment of tissue oxygenation. "Thus, TRPA1 channel regulation may provide new therapeutic targets for ischemic diseases, particularly in improving blood flow and reducing neuroinflammation." (PMID 40895091, 2024).
ischemic heart disease (1 paper, 2024). "First of all, a genome-wide association study revealed that TRPA1 variant at rs12541758 is the strongest susceptibility allele for coronary artery disease in humans, which provided the most conspicuous association between TRPA1 and ischemic heart disease." (PMID 39323758, 2024). "Firstly, it suggests that modulation of TRPA1 channels may offer novel strategies for managing hypertension, ischemic heart disease, and peripheral vascular disorders." (PMID 39323758, 2024). "In the context of ischemic heart disease, the role of TRPA1 has garnered considerable interest." (PMID 39323758, 2024).
keratitis (1 paper, 2022). A corneal disease that is characterized by inflammation of the cornea. "Moreover, TRPA1 was evaluated in a UV-induced keratitis in guinea pigs." (PMID 36145607, 2022). "Thus, TRPA1 activation could explain the increase in nocifensive behaviors in UV-induced keratitis." (PMID 36145607, 2022).
kidney tumours (1 paper, 2024). "Early data-driven analysis showed that TRPA1 is overexpressed in kidney tumours, and high expression indicates better patient survival." (PMID 39770499, 2024).
knee osteoarthritis (1 paper, 2016). "Chronic arthritis was induced by complete Freund’s adjuvant (CFA), knee osteoarthritis by monosodium iodoacetate (MIA) in TRPA1 knockout (KO) mice and C57Bl/6 wildtype mice." (PMID 26746673, 2016).
lactic acidosis (1 paper, 2018). Metabolic acidosis characterized by the accumulation of lactate in the body. "Mitochondrial encephalopathy that is associated with lactic acidosis and stroke-like episodes (MELAS) might also involve TRPA1-mediated headache mechanisms, since lactic acidosis-induced acidosis should activate human TRPA1." (PMID 30388732, 2018).
lymphoma (1 paper, 2017). A malignant (clonal) proliferation of B- lymphocytes or T- lymphocytes which involves the lymph nodes, bone marrow and/or extranodal sites. "Interleukin-31 (IL-31), T helper cell type 2- derived cytokine, activates a small subpopulation of primary sensory neurons expressing TRPV1, and TRPA1 through IL-31 receptor, and produced inflammatory and lymphoma-associated itch." (PMID 28515697, 2017).
meningioma (1 paper, 2024). A generally slow growing tumor attached to the dura mater. "Moreover, expression levels of Beclin, LC3B, HST1, TRPV1, TRPA1, Nrf2, and DDX3X did not associate with OS of meningioma patients (p>0.05)." (PMID 38758750, 2024).
metastatic cancer (1 paper, 2021). A carcinoma which has spread from the original site of growth to another anatomic site. "It is an open question the role of TRPA1 channel in CD8+ T cells in a metastatic cancer model, and further studies are necessary." (PMID 34041030, 2021).
nasal polyps (1 paper, 2021). "However, immunohistochemistry revealed TRPA1 expression in human mast cells of skin lesions and nasal polyps." (PMID 34768891, 2021).
nasopharyngeal squamous cell carcinoma (1 paper, 2023). A squamous cell carcinoma that arises from the nasopharynx. "For example, human nasopharyngeal squamous cell carcinoma cells express functional TRPA1 and TRPV1 channels." (PMID 37240443, 2023).
Nausea (1 paper, 2018). A sensation of unease in the stomach together with an urge to vomit. "THCA is a TRPA1 partial agonist, and TRPM8 antagonist which may underlie a potential role in analgesia, and has been shown to have anti-inflammatory and anti-nausea properties." (PMID 29797104, 2018).
Neurogenic bladder (1 paper, 2023). A type of bladder dysfunction caused by neurologic damage. "To further investigate the role of TRPA1 in bladder fibrosis in vivo, we investigated the expression of TRPA1 and fibrotic changes in the bladder mucosa of patients with neurogenic bladders (n = 3) resulting from spinal cord injury." (PMID 37298451, 2023). "In the present study, the TGF-β1-induced downregulation of TRPA1 was observed in cultured subu−MyoFBs, in the bladder mucosa of SCI rats as well as in the mucosa of neurogenic bladder patients." (PMID 37298451, 2023).
oral lichen planus (1 paper, 2022). Oral lichen planus is a chronic inflammatory oral condition of unknown aetiology characterized by T-cell-mediated chronic immune response and abnormal epithelial keratinization cycle. "Large proportions of the dermal macrophages of the AD-dogs showed TRPA1-IR; this evidence was consistent with the data provided in the buccal samples of human patients with oral lichen planus and in skin samples of IL-13–induced chronic AD in mice." (PMID 36187821, 2022).
Osteopenia (1 paper, 2024). Osteopenia is a term to define bone density that is not normal but also not as low as osteoporosis. "Finally, TRPA1 knockdown targeting macrophages by adeno-associated virus-9 could relieve osteoclast differentiation and osteopenia in ovariectomized mice." (PMID 39191723, 2024). "Moreover, TRPA1 inhibition prevented osteopenia induced by OVX in vivo." (PMID 39191723, 2024).
peripheral arterial disease (1 paper, 2019). A disorder of the arteries supplying the upper and lower extremity and the visceral organs. "In hindlimb ischemia as a model for peripheral arterial disease, spontaneous pain-related behaviour during reperfusion was reduced in TRPA1 knockouts and by TRPA1 inhibition." (PMID 31547502, 2019). "For these major disease entities, but also for peripheral artery disease, pre-clinical studies suggest the role of TRPA1." (PMID 31547502, 2019).